INS (insulin)
Diseases named in the same sentence as INS in open-access papers (continued):
Sharing a sentence is not in itself a finding about the gene and the disease.
Hypoglycemia (continued). "The BITS includes factors such as attitudes toward fear of injection and self-testing, expectations regarding positive insulin treatment, expected hardships of insulin treatment, stigmatization of insulin injections, and fear of hypoglycemia." (PMID 30807441, 2019). "The glucose dynamics in daytime and nighttime are quite different due to meals and activities, and having a dedicated algorithm for the postprandial hypoglycemia would improve the AP’s insulin dosing during the daytime benefitting the patient significantly." (PMID 31694629, 2019). "Attenuation of microglia activation results in improved counterregulatory responses to glucopenia and less severe insulin-induced hypoglycemia." (PMID 30996341, 2019). "Hypoglycemia that results from exogenous insulin administration can also manifest with symptoms resembling those of IAS." (PMID 31883520, 2019). "The Medtronic Guardian Sensor 3 CGM can also be used in conjunction with insulin injections and features prediction of highs and lows with an alert 10–60 min prior to hyper- or hypoglycemia." (PMID 30875898, 2019). "A cumbersome administration method and a high chance of side effects such as hypoglycemia and weight gain have made insulin a problematic and debatable option in the prevention of GDM." (PMID 31720147, 2019). "A notable experimental problem was that CL induced hypoglycemia during the insulin tolerance testing procedure." (PMID 30804793, 2019). "Differences between sexes are also apparent in the use of oral anti-diabetic drugs, which is somewhat less in females, while their rate of insulin-mediated hypoglycemia seems to be more frequent than that seen in males." (PMID 31830073, 2019). "Detemir led to a greater response of autonomic and neuroglycopenic symptoms, albeit at lower blood glucose levels than human insulin, which would suggest a lowering of the awareness of hypoglycemia." (PMID 30696060, 2019). "Overall, 40% of marked hypoglycaemia were preceded by violation of the presumed insulin rate during P2 compared to 8% during P1." (PMID 30689675, 2019). "This list included but was not limited to questions pertaining to the artificial pancreas, prevention of hypoglycemia, insulin pump therapy and long-term effects of various insulin analogs." (PMID 30787908, 2019). "The autonomous production of excessive amounts of insulin, which results in hypoglycemia, is the classical feature of this tumor, and β-cell adenomas cannot decrease insulin secretion in the presence of hypoglycemia." (PMID 32009878, 2019). "The incremental costs were mainly driven by the increased cost of insulin, partially offset by lower costs of hypoglycaemia in the degludec group." (PMID 31796048, 2019). "With regard to clinical features of diabetic patients who developed hypoglycemia, patients of Group 1 had significantly lower insulin secretion and were high among insulin users in the present study." (PMID 30815039, 2019). "Insulin pump settings and patient’s glucose management resulted in very effective hypoglycemia prevention." (PMID 30443779, 2019). "Depending on the specification of the individual insulin therapy, both basal or pre-meal bolus adaptations are possible strategies to prevent hypoglycemia during moderate-intensity exercise." (PMID 31835538, 2019). "Patients will report all events of symptomatic hypoglycaemia including date, time of episode, the accompanying measurement of plasma glucose, symptoms, awake or asleep, and time for last bolus insulin administration." (PMID 31337371, 2019). "The most critical diagnostic criterion is the detection of an inappropriately elevated plasma insulin level under conditions of hypoglycemia." (PMID 32009878, 2019).
Hypoglycemia (continued). "The current data showed that 27.3% and 61.6% of patients were using insulin and sulphonylureas and were higher than a study conducted in Colombia in which sulphonylureas use was found in 23.4%, and insulin in 20.7% this could in part explain the high risk of hypoglycemia in the current sample." (PMID 30819208, 2019). "For these patients, insulin long-term usage often leads to unwanted side effects such as ectopic fat deposition and disabling episodes of hypoglycemia." (PMID 31920961, 2019). "Antecedent insulin-induced hypoglycemia reduces activation of adrenergic neurons in medullary C1 and C3 nuclei after subsequent hypoglycemia." (PMID 31013147, 2019). "There are several treatments for diabetes, with the most common treatment regimen being the prescription of oral antihyperglycemic agents and insulin therapy which consequently induce hypoglycemia." (PMID 31772942, 2019). "The sensation of hypoglycemia can differ broadly between people, as clinicians experienced in performing insulin tolerance tests are aware." (PMID 31777577, 2019). "Dextrose-containing fluids should be started along with the insulin infusion to avoid hypoglycemia, with a target serum glucose level of 150–200 mg/dL." (PMID 31488052, 2019). "Given concern for nocturnal hypoglycemia, and patient interest in steroid-sparing anti-hypoglycemic regimen, she was also started on overnight continuous subcutaneous glucagon infusion via insulin pump." (PMID 29340167, 2018). "The NMA results showed that DPP-4i, TZD, Met, basal insulin, and GLP-1RA were more strongly associated with hypoglycemia, compared with placebo." (PMID 30148851, 2018). "In order to reduce hypoglycemia frequency, importance and length these technologies helps patients adjust their insulin treatment based on real-time feedback from the CGM function." (PMID 30713524, 2018). "To examine the hypoglycemia premise, we developed an experimental murine model in which insulin was administered to mice under normo- and hypoglycemic conditions." (PMID 30167086, 2018). "The islet size and the expression of insulin were significantly increased in P. falciparum malaria patients with hypoglycaemia." (PMID 29993021, 2018). "The patients should be educated on monitoring of glucose, insulin injection technique, insulin storage, recognition/treatment of hypoglycemia, and sick day management by qualified health educators." (PMID 29508275, 2018). "Whereas a systemic negative bias will slightly raise HbA1c, a positive systemic bias will reduce HbA1c but increase the number of severe hypoglycemia episodes, total daily insulin use, and number of fingersticks per day." (PMID 28946757, 2018). "Although insulin-induced hypokalemia is well known, few studies have explored the changes in serum sodium, chloride, and calcium in response to hypoglycemia." (PMID 30105256, 2018). "Considering dose titration phases, the proportion of patients experiencing hypoglycemia episodes during the titration period was higher for insulin analogues than for NPH in the first trials." (PMID 29649221, 2018). "Substantial elevation of GLP-1 and insulin responses after PTG likely contribute to the observed hypoglycemia, and mirror similar hormone levels and complications observed in bariatric weight loss patients." (PMID 29548882, 2018). "Laboratory investigations revealed hypoglycemia (serum glucose level: 30 mg/dL) with a high insulin level of 50 IU/L." (PMID 29513222, 2018). "Continuous blood glucose–monitoring devices and computer-assisted closed loop systems for insulin delivery have been shown to prevent hypoglycemia and reduce glucose variability in ICU settings." (PMID 29300728, 2018). "In response to insulin-induced hypoglycemia, which is expected to activate the HPA axis due to the brain sensing decreased plasma glucose, there is an attenuated plasma cortisol or corticosterone response in SLE." (PMID 30287776, 2018).
Hypoglycemia (continued). "Overall, individuals with cognitive dysfunction have difficulty performing self-care (e.g. matching insulin dosage to carbohydrate intake or avoiding and treating hypoglycaemia), leading to a significantly reduced quality of life." (PMID 29417185, 2018). "Hospitals need to have a policy and procedure in place for recognizing and treating hypoglycemia, particularly if there are plans to institute more intensive insulin therapy." (PMID 29255628, 2018). "The hypoglycemia is insulin- and TNF-α-independent and is paralleled by exhaustion of hepatic glycogen stores without increased gluconeogenesis." (PMID 30375380, 2018). "Attenuation of insulin delivery for impending late postprandial hypoglycemia allows reduction of the duration and severity of hypoglycemia that would otherwise be experienced in similar OL scenarios." (PMID 30070928, 2018). "In the automated insulin dosing scenario, for example, decisions would need to be made at the onset of exercise to prevent exercise-induced hypoglycemia." (PMID 30530451, 2018). "Conversely, when glucose is no longer absorbed from the gastrointestinal tract, HGP will increase to avoid hypoglycemia through declining insulin secretion from pancreatic islets." (PMID 30275974, 2018). "Proper patient education regarding monitoring of glucose, insulin injection technique, insulin storage, recognition/ treatment of hypoglycemia, and sick day management is imperative." (PMID 29527102, 2018). "Incretin-based therapies, particularly GLP-1 receptor agonists, provide postprandial control with lower risks of hypoglycemia than prandial insulin." (PMID 29527102, 2018). "The slope of sensor glucose prior to hypoglycaemia was steeper during closed‐loop intervention than during control intervention (P < .01), while insulin delivery was reduced (P < .01)." (PMID 29577536, 2018). "Relative insulin excess increases glucose uptake and suppresses hepatic glucose production despite development of hypoglycaemia, and also acts peripherally to limit lipolysis and the delivery of gluconeogenic substrates to the liver." (PMID 29417183, 2018). "Simulations are only valid for predicting cohort-level responses, such as average glycemia and variability, safety from hypoglycemia, and required insulin/nutrition inputs." (PMID 30071851, 2018). "Mice lacking VGLUT2 selectively in steroidogenic factor 1 neurons that mark the VMH have defective CRR to insulin-induced hypoglycemia." (PMID 29593556, 2018). "In patients with T1D and problematic hypoglycemia, switching basal insulin to degludec resulted in a significant reduction in both HbA1c and total basal insulin dose without a corresponding increase in bolus dose." (PMID 29549574, 2018). "The ability to switch off endogenous insulin release during falling blood glucose is an important and sometimes under-appreciated defence against hypoglycemia." (PMID 30146176, 2018). "The IRs of nocturnal hypoglycemia were highest in patients with T1DM using short-acting insulin in the 4-week retrospective period (20.5 events ppy) and lowest in the 4-week prospective period in T2DM patients using short-acting insulin (1.1 events ppy)." (PMID 29433560, 2018). "Insulin, proinsulin and C-peptide concentrations were obtained during hypoglycaemia, defined as a blood glucose below 2.5 mmol/L (neonatal period), or below 3.2 mmol/L (thereafter)." (PMID 29116340, 2018). "Weight, BMI, HbA1c, lipid profile, uric acid, creatinine, microalbuminuria, daily insulin requirements, and number of episodes of hypoglycemia (blood glucose < 70 mg/dL) were the main outcomes evaluated." (PMID 29791661, 2018). "In the present analysis, we report the incidence of clinically significant hypoglycaemia at 144 episodes per patient‐year during insulin pump therapy using sensor glucose data." (PMID 29577536, 2018).
Hypoglycemia (continued). "Opposed to the artificial pancreas, which administers either insulin or glucagon depending on the blood glucose level, we investigated whether coadministration of a fixed ratio of the two hormones could reduce the risk of hypoglycemia when treating diabetic rats." (PMID 29595915, 2018). "Given the prolonged mechanism of action of many oral diabetic agents and long-acting insulin, extended in-hospital observation for possible recurrent hypoglycemia is advocated by many commonly utilized resources." (PMID 29799604, 2018). "In the clinical trial setting, the use of these analogues has also been associated with fewer hypoglycemic episodes compared with NPH insulin, especially when comparing nocturnal hypoglycemia rates." (PMID 29460260, 2018). "The premix insulin analogues are preferred over human premix insulins owing to the lower incidence of severe hypoglycemia, less nocturnal hypoglycemia, and flexibility of administration." (PMID 29508275, 2018). "Doctors suspected self-inflicted hypoglycemia by taking extra insulin dosages and discussed with Ahmed who admitted this practice." (PMID 29682577, 2018). "All 7 individuals with recurrent hypoglycemia who were taking insulin were taking long-acting insulin preparations." (PMID 29799604, 2018). "Data collected included fasting (FBG), pre- and post-prandial whole blood glucose, insulin dose, reasons for insulin switching and hypoglycemia." (PMID 29862021, 2018). "It is characterized by spontaneous postprandial hypoglycemia, high levels of immunoreactive insulin, and anti-insulin antibodies." (PMID 30462811, 2018). "The association of human insulin with MET was the most frequent therapy and the occurrence of severe hypoglycemia was 3.1%." (PMID 30386438, 2018). "T1DM patients who partake in high-intensity aerobic training (AThigh) to reduce CVD often utilize conventional insulin therapy (CIT; 9–15 mmol/L) to offset the risk of hypoglycemia." (PMID 30116746, 2018). "Dietary restrain and restriction of favorable sweets can encourage extra insulin overdose to get the restrained sweet as a way of hypoglycemia correction (case scenario I b)." (PMID 29682577, 2018). "Contrasting observations have been obtained concerning the role of altered insulin sensitivity in the development of juvenile hypoglycemia." (PMID 29678421, 2018). "Changes in HbA1c, 30-day mean fasting plasma glucose (mean FPG), daily insulin dose, and severe hypoglycemia rates were collected at basal insulin switch (T0), 3-months (T1), 6-months (T2), and 12-months (T3) after IDeg was started." (PMID 30190702, 2018). "In the early 60’s, an intravenous (i.v.)insulin pump delivering insulin and glucagon to counteract hypoglycemia was reported by Kadish (1964)." (PMID 32232090, 2018). "Symptomatic hypoglycemia for individuals taking insulin and oral diabetic medications is a common medication-related complication leading to emergency department (ED) presentations, accounting for 13.3% of all adverse drug reaction visits." (PMID 29799604, 2018). "The reduction in insulin signaling in the muscle decreases glucose utilization, towards the goal of preventing hypoglycemia, however this is a limited mechanism." (PMID 29760586, 2018). "Oral glucose tolerance test (OGTT) showed hypoglycemia at the 30th minute (glucose: 25 mg/dL) with an insulin level of 300 IU/L." (PMID 29513222, 2018). "Exposure to insulin-related hypoglycaemia was reported to lead to poor insulin adherence and omission." (PMID 29788908, 2018). "The potential effect of AIA on safety, particularly as related to hypersensitivity reactions, hypoglycemia, and treatment-emergent adverse events, as well as on glycemic control (HbA1c, insulin dose), was evaluated." (PMID 29355435, 2018). "HCPs identified fear of hypoglycaemia as a significant issue in optimal insulin use in surveys and interviews.“I think the effect of getting older is that they hate the idea of hypoglycaemia as well." (PMID 29788908, 2018).
Hypoglycemia (continued). "The occurrence of hypoglycemia at the 30th minute of the OGTT with a high insulin level is noteworthy and supports a vagal effect." (PMID 29513222, 2018). "The management of DM1 in adolescents and children has some critical issues, in particular in preschool children, such as very low insulin requirements, unpredictable eating patterns and physical activity and more frequent hypoglycaemia, especially at night." (PMID 29954380, 2018). "Congenital hyperinsulinism (CHI) is a heterogeneous metabolic disorder that is characterized by the unregulated release of insulin from pancreatic beta cells leading to recurrent episodes of hypoglycaemia." (PMID 30577875, 2018). "Predictors of having any hypoglycemia included the higher frequency of blood glucose monitoring, longer duration of insulin therapy, and T1DM." (PMID 30479669, 2018). "The results confirmed a reduced rate of nocturnal hypoglycemia and superior glycemic control in comparison with insulin pump treatment." (PMID 29848472, 2018). "We evaluated sensor glucose excursions and basal insulin infusion rates prior to and post hypoglycaemia." (PMID 29577536, 2018). "The primary outcome is to determine the safety of mandatory insulin therapy in critically ill patients using the number of episodes of hypoglycaemia and hypokalaemia per unit length of stay in intensive care." (PMID 29519778, 2018). "Frequency of hypoglycemia recurrence requiring repeat ED visits was more common in those taking oral agents compared to individuals taking insulin alone (p = 0.04)." (PMID 29799604, 2018). "There have been many observational studies of CSII in individuals with suboptimal glucose control or who experience problematic hypoglycaemia despite multiple daily injections (MDI) of insulin." (PMID 29423581, 2018). "In general, a clinical goal of a HbA1c near 7.0 mg% is set to prevent the lethal effects of hypoglycemia from the lowering of blood sugars by conventional insulin therapy." (PMID 29951281, 2018). "The UK Hypoglycemia Study Group report that the incidence of severe hypoglycemia increased from 7 to 25% in patients treated with insulin for < 2 years with those treated for > 5 years." (PMID 29527102, 2018). "Regarding their medication regimens, the number of patients on hypoglycemia-inducing oral hypoglycemic agents (OHAs), namely, sulfonylureas and meglitinide analogues, insulin, or both, was 36, 215, and 18, respectively." (PMID 30473710, 2018). "In a study evaluating altered vagal and intestinal mechanosensory function in patients with chronic unidentified dyspepsia, the pancreatic polypeptide response to insulin induced hypoglycemia had been shown to diminished." (PMID 29914168, 2018). "As such, increased use of hypoglycemia-inducing agents (insulin, sulfonylureas) is common in this population." (PMID 30252913, 2018). "Although we observed a reduction in the mean evening insulin dose, the mean morning insulin dose, body weight, and hypoglycemia frequency were identical in both phases." (PMID 30127860, 2018). "Intravenous insulin is the mainstay of treatment even in patients with normal glucose levels; however, intravenous dextrose should be given to avoid hypoglycemia." (PMID 30151400, 2018). "Three insulin treated patients needed an insulin dose reduction due to documented hypoglycemia (10% of all treated patients and 17.6% of insulin treated patients)." (PMID 30402450, 2018). "Concerning nocturnal hypoglycemia, it was available from 20 clinical trials, and the meta-analysis results favor insulin analogues (RR 0.66; 95% CI 0.57; 0.76; I2 97.1%), meaning that the risk of having a hypo episode was reduced." (PMID 29649221, 2018). "Study endpoints included changes in glycemic control, basal insulin dose, rates of hypoglycemia, and changes in hypoglycemia unawareness status and QoL." (PMID 29549574, 2018).